PFKFB4 (6-phosphofructo-2-kinase/fructose-2,6-biphosphatase 4)
Diseases named in the same sentence as PFKFB4 in open-access papers (continued):
Sharing a sentence is not in itself a finding about the gene and the disease.
melanoma (continued). "What is more, our recent analysis revealed that high PFKFB4 expression contributes to the poor prognosis of malignant melanoma patients and correlates with significantly worse distant metastasis-free survival and shorter overall survival." (PMID 34445551, 2021). "So far only very limited information related to the expression and the role of PFKFB4 isoenzyme in melanoma has been collected." (PMID 34445551, 2021). "An approximately two-fold increase in PFKFB4 expression in hypoxia in both melanoma cell lines was observed." (PMID 34445551, 2021). "This indicates that induction of PFKFB4 gene expression can be considered a crucial mechanism behind glycolysis enhancement in hypoxic melanoma cells." (PMID 34445551, 2021). "Our work has shown that only isoform-specific expression analysis provides a complete picture of changes in PFKFB4 levels in melanoma cells." (PMID 34445551, 2021). "Our research has shown that five isoforms of PFKFB4 (B, C, D, E, F) are expressed in the tested melanoma cell lines (WM266-4 and WM115)." (PMID 34445551, 2021). "In melanoma, PFKFB4 has been shown to activate the RAS/AKT pathway, impacting cell migration." (PMID 39595571, 2024). "Here, however, we explore a novel function of PFKFB4 in melanoma cell migration." (PMID 35914811, 2022). "Whether PFKFB4 repression by LXX-8250 treatment in melanoma cells leads to glycolysis inhibition attracted our attention." (PMID 36034839, 2022). "Moreover, because xPFKFB4 efficiently rescued the PFKFB4 depletion phenotype in human melanoma cells, we postulated that the protein function we looked for was evolutionarily conserved between human and X. laevis PFKFB4." (PMID 35914811, 2022). "Here, we have analyzed the importance of PFKFB4 in melanoma cell migration." (PMID 35914811, 2022). "Melanomas present higher expression of PFKFB4 mRNA compared with other tumors." (PMID 35914811, 2022). "Therefore, we focused on the role of PFKFB4 in the effects of LXX-8250 in melanoma, and confirmed the downregulation of PFKFB4 expression by LXX-8250 treatment." (PMID 36034839, 2022). "As PFKFB4 protein seemed to control melanoma cell migration independently of its enzymatic activities, we looked for interacting protein partners using mass spectrometry after immunoprecipitation of a FLAG-tagged form of human PFKFB4 expressed in the MeWo cells." (PMID 35914811, 2022). "Furthermore, the melanoma cells with PFKFB4 overexpression were resistant to the reduction of the levels of lactic acid and F-1,6-BP by LXX-8250 treatment." (PMID 36034839, 2022). "Therefore LXX-8250 works as a novel suppressor of PFKFB4 to inhibit autophagic flux and induce apoptosis in melanoma." (PMID 36034839, 2022). "Another enzyme involved in glycolysis, PFKFB4 (6-phosphofructo-2-kinase/fructose-2,6-biphosphatase 4), was also demonstrated to be upregulated following exposure to hypoxia and its high expression correlated with poor prognosis of melanoma patients." (PMID 33918883, 2021). "Cancer-specific isoenzyme of phosphofructokinase II (PFKFB4), as our previous research has shown, may be one of the most important enzymes contributing to the intensification of glycolysis in hypoxic malignant melanoma cells." (PMID 34445551, 2021). "Our current study provides novel information about additional PFKFB4 isoforms and alternative splicing events that may be crucial for cancer-specific metabolic changes in melanoma cells." (PMID 34445551, 2021). "Moreover, the analysis at the protein level allowed the selection of those isoforms whose functional validation should be performed to fully understand the importance of PFKFB4 expression in the metabolic adaptation of malignant melanoma cells." (PMID 34445551, 2021). "It would be crucial to determine whether isoform B or D constitute the canonical isoform of PFKFB4 in melanoma cells." (PMID 34445551, 2021).
melanoma (continued). "Based on the presented data we presume that because the isoforms with the highest expression in melanoma cells are the D and F isoforms, the cells may demonstrate not only a functional PFKFB4 protein but also increased phosphatase activity due to the presence of the F isoform." (PMID 34445551, 2021). "This unconventional activity links the metabolic regulator PFKFB4 to RAS-AKT signaling and impacts melanoma cell migration." (PMID 35914811, 2022). "To explore the role of PFKFB4 further in LXX-8250’s effects, first we examined the influence of PFKFB4 on the cell proliferation of melanoma cells." (PMID 36034839, 2022). "The crosstalk between key regulators of glycolysis and Warburg effect (PFKFB4) and a pleiotropic cell signaling pathway (ICMT–RAS) further increases the complexity of the network known to promote melanoma cancer progression." (PMID 35914811, 2022). "To extend this finding to other melanoma contexts, we examined AKT activation in three other cell lines after PFKFB4 depletion." (PMID 35914811, 2022). "In sum, our study has demonstrated a novel, glycolysis-independent function of PFKFB4, promoting the interaction between ICMT and RAS, resulting in active migration of both melanoma cells and melanocytes." (PMID 35914811, 2022). "From this series of results, we concluded that the interaction between PFKFB4 and ICMT was critical for controlling RAS subcellular localization and melanoma cell migration." (PMID 35914811, 2022). "Our study further defines a novel, glycolysis-independent function for PFKFB4, which promotes ICMT–RAS interactions, results in efficient RAS localization at the plasma membrane, activates AKT signaling and enhances melanoma cell migration." (PMID 35914811, 2022). "Using RT-qPCR and semi-quantitative RT-PCR, we presented the PFKFB4 gene expression profile at the level of six isoforms described in the OMIM NCBI database in normoxic and hypoxic melanoma cells." (PMID 34445551, 2021). "PFKFB4 and CAIX expression is upregulated during hypoxia in melanoma-derived cancer cells." (PMID 37892173, 2023). "All these data together indicated that PFKFB4 controlled human melanoma cell migration via a novel nonconventional function controlling the RAS/PI3K/AKT pathway." (PMID 35914811, 2022). "The same trend was observed for PFKFB4, as the expression of the protein was comparable regardless of the duration of hypoxia stimulation of melanoma cells (data not shown)." (PMID 34445551, 2021). "Although the PFKFB4 gene seems to play a crucial role in the progression of melanoma, so far there are no complete data on the expression of PFKFB4 at the isoform level and the influence of hypoxia on alternative splicing." (PMID 34445551, 2021). "This suggested that PFKFB4 influenced AKT signaling in several but not all melanoma cell contexts." (PMID 35914811, 2022). "However, in melanoma cell lines, a tumor type with generally high PFKFB4 levels, we did not observe a strict correlation between PFKFB4 expression levels and the metastatic characteristics of the cells." (PMID 35914811, 2022).
hepatocellular carcinoma (11 papers, 2016 to 2024). A malignant tumor that arises from hepatocytes. "The lncRNA FIRRE expression was elevated in hepatocellular carcinoma and associated with MBNL3 for promoting the splicing activity of PXN or PFKFB4 for glycolysis." (PMID 38556083, 2024). "In adult hepatocellular carcinoma, PFKFB4 has been identified as a metabolic driver of disease progression and chemoresistance through its mitigation of reactive oxygen species (ROS)." (PMID 39595571, 2024). "PFKFB4, which is a regulator of glycolysis, has been found to be overexpressed in various types of cancer, including hepatocellular carcinoma." (PMID 39595571, 2024). "Aroel for FIRRE has also been reported in hepatocellular carcinoma through the regulation of PFKFB4 expression." (PMID 35893227, 2022). "PFKFB4 was required for peroxisome proliferator-activating receptor γ (PPARγ)-stimulated glycolysis in hepatocellular carcinoma." (PMID 33593309, 2021). "In hepatocellular carcinoma (HCC), PPARγ, phosphorylated at Ser84, promoted PFKFB4 transcription, thereby promoting glycolysis to maintain HCC progression." (PMID 37024456, 2023). "By boosting CREB-mediated PFKFB4 transcription and expression, the highly expressed FIRRE promoted hepatocellular carcinoma cell proliferation and glycolysis." (PMID 35669241, 2022).
bladder cancer (10 papers, 2019 to 2025). "It has been revealed that PFKFB4 is highly expressed in many types of human tumors, including breast, prostate, and bladder cancers, indicating that PFKFB4 plays an essential role in tumor development and/or progression." (PMID 36300085, 2022). "Interestingly, recently published data also revealed the negative impact of PFKFB4 on breast and bladder cancer patients but it was not noticable in the data sets we have analyzed." (PMID 31754349, 2019).
gastric cancer (9 papers, 2020 to 2025). A primary or metastatic malignant neoplasm involving the stomach. "For instance, patients with low PFKFB4 expression in gastric cancer had significantly longer overall survival (OS), initial progression survival, and post-progression survival durations compared to those with high PFKFB4 expression." (PMID 37770581, 2023). "Pfkfb4 is a biomarker for predicting the poor prognosis of gastric cancer patients." (PMID 35634481, 2022).
pancreatic cancer (7 papers, 2020 to 2025). "Targeting SP1 or its downstream effector PFKFB4 effectively inhibits tumorigenesis and tumor growth in both mouse models and patient‐derived organoid models of pancreatic cancer." (PMID 40832790, 2025). "In breast, bladder, and pancreatic cancer and other malignant tumors, targeting the glycolysis pathway mediated by PFKFB4 can inhibit the growth and invasion of tumor cells." (PMID 35938165, 2022). "It was found that PFKFB4 was overexpressed under hypoxia in gastric and pancreatic cancer cells and contributed to cancer cells proliferation and survival." (PMID 33593309, 2021). "Other investigation also showed that bruceine A could induce cell growth inhibition and apoptosis via 6-phosphofructo-2-kinase/fructose-2,6-bisphosphatase 4 (PFKFB4)/GSK3β signaling in pancreatic cancer cells (Zhang." (PMID 35370639, 2022). "Combination therapy targeting SP1 and PFKFB4 demonstrates significant efficacy in pancreatic cancer models in vivo, without observable toxicity." (PMID 40832790, 2025).
cervical cancer (6 papers, 2021 to 2024). A primary or metastatic malignant neoplasm involving the cervix. "For example, the loss of PFKFB4 induces cell cycle arrest in cervical cancer cells." (PMID 37919747, 2023). "PFKFB4 expression has also been found to be increased by carbonic anhydrase IX, promoting motility in human cervical cancer cells." (PMID 39595571, 2024). "To determine the association between CAIX and PFKFB4 expression in human cervical cancer, we analyzed the mRNA expression of CAIX and PFKFB4 in data sets from TCGA and the Gene Expression Omnibus database (GSE29570 and GSE52903)." (PMID 33803236, 2021). "In summary, our present study highlights the importance of a signaling pathway, in cervical cancer, with a significant association between CAIX, PFKFB4, and the EMT proteins E-cadherin and vimentin." (PMID 33803236, 2021). "The cervical cancer patients with a high CAIX level and high PFKFB4 level (CAIXhigh/PFKFB4high) were more predisposed to advanced clinical stage and lymph node metastasis than those expressing CAIXlow/PFKFB4low, CAIXhigh/PFKFB4low, and CAIXlow/PFKFB4high." (PMID 33803236, 2021). "A positive correlation was found between CAIX expression and PFKFB4 levels in the cervical cancer of the TCGA database." (PMID 33803236, 2021). "PFKFB4 plays a role in the motility of cervical cancer cells." (PMID 37919747, 2023). "The results indicate that PFKFB4 may regulate the migratory ability of cervical cancer cell lines." (PMID 33803236, 2021). "CAIX overexpression increased the expression of 6-Phosphofructo-2-Kinase/Fructose-2, 6-Biphosphatase 4 (PFKFB4) and EMT, and promoted the migration of cervical cancer cells." (PMID 36497465, 2022). "The survival analysis and Kaplan–Meyer curves were performed taking into consideration the high or low expression of PFKFB4 and RIPOR2, according to the median expression levels, in TCGA cervical cancer samples." (PMID 36497200, 2022). "What is more, cervical cancer patients, that exhibit high both CAIX and PFKFB4 expression demonstrate shorter overall survival." (PMID 34445551, 2021). "A significantly correlation was observed between PFKFB4 and CAIX expression in human lung adenocarcinoma xenografts; however, how PFKFB4 is involved in cervical cancer is unclear at present." (PMID 33803236, 2021). "Our study found that CAIX overexpression increases PFKFB4 expression and EMT, promoting cervical cancer cell migration." (PMID 33803236, 2021). "Moreover, we considered that, in terms of the survival rate of cervical cancer patients, some of the mechanisms and influences regulated by CAIX/PFKFB4 have not yet been discovered." (PMID 33803236, 2021).
lung adenocarcinoma (6 papers, 2014 to 2023). A carcinoma that arises from the lung and is characterized by the presence of malignant glandular epithelial cells. "In our study we found that PFKFB4 was overexpressed in lung adenocarcinoma associated with SRC family protein and had an interaction with SRC-2." (PMID 33593309, 2021). "PFKFB4 expression is increased in lung adenocarcinoma and this increase can promote the oncogenic phenotypes of lung adenocarcinoma cells." (PMID 37179372, 2023). "To understand the precise molecular mechanism of PFKFB4-SRC-2-drived lung adenocarcinoma progression, we overexpressed CARM1 in si-SRC-2 #1-transfected LUAD cells, of which SRC-2 had been mostly knockdown." (PMID 33593309, 2021). "Our research reveal that PFKFB4 promotes lung adenocarcinoma cells proliferation, migration and invasion via enhancing phosphorylated SRC-2-mediated CARM1 expression." (PMID 33593309, 2021). "To identify the potential mechanism of PFKFB4-SRC-2 in lung adenocarcinoma, we performed a transcriptome sequencing using A549 cells transfected with si-SRC-2 #1 and si-NC." (PMID 33593309, 2021). "Functionally, PFKFB4 promoted lung adenocarcinoma cells proliferation, migration and invasion by phosphorylating SRC-2." (PMID 33593309, 2021). "H460 cells are lung adenocarcinoma cells that harbor several common oncogenic mutations (CDKN2Adel457, KRASQ61H, PIK3CAE545K, STK11Q37X) and are sensitive to inhibition of PFKFB4 using siRNA molecules." (PMID 26221874, 2015). "Further examination of a larger cohort of lung adenocarcinomas and adjacent normal tissues from 18 patients by immunohistochemical analyses revealed high PFKFB4 protein expression relative to normal lung alveoli." (PMID 25115398, 2014). "Taken together, these data showed that overexpression of CARM1 could abolish the suppressed effects induced by PFKFB4 knockdown, which suggested that PFKFB4 promoted lung adenocarcinoma cells proliferation through SCR-2/CARM1 axis." (PMID 33593309, 2021). "Furthermore, we identified that CARM1 was transcriptionally regulated by SRC-2 and involved in PFKFB4-SRC-2 axis on lung adenocarcinoma progression." (PMID 33593309, 2021). "Furthermore, endogenous co-immunoprecipitation results also confirmed that PFKFB4 interacted with SRC-2 in lung adenocarcinoma cells A549 and NCI-H1975." (PMID 33593309, 2021). "However, the exact function and regulatory mechanism of PFKFB4 in lung adenocarcinoma (LUAD) is less understood." (PMID 33593309, 2021). "Moreover, the suppressed proliferation ability of PFKFB4 knockdown in lung adenocarcinoma cells was reversed upon overexpression of CARM1 in PFKFB4-knockdown A549 and NCI-H1975 cells." (PMID 33593309, 2021). "Although the differences in metabolic functions of PFKFB3 and PFKFB4 are poorly understood, we observed a more robust induction of PFKFB4 protein relative upon exposure of H460 cells to 1% oxygen and significant correlation between hypoxia and PFKFB4 expression in lung adenocarcinoma tissues." (PMID 25115398, 2014). "A PFKFB4 siRNA was found to reduce F2,6BP and glycolytic flux to lactate in A549 lung adenocarcinoma cells (U.S. Patent #8,283,332) and two other PFKFB4 siRNAs were independently observed to reduce lactate secretion and the intracellular ATP in malignant glioma cells." (PMID 25115398, 2014). "We examined serial sections of human H460 lung adenocarcinoma xenograft tumors resected from athymic mice for expression of PFKFB4 and PFKFB3 and correlated the expression levels of these proteins using carbonic anhydrase IX, a potent transcriptional target of HIF-1α, as a hypoxia marker." (PMID 25115398, 2014). "In our study, we found that PFKFB4 was overexpressed in lung adenocarcinoma tissues and cell lines (A549 and NCI-H1975) and further revealed the regulatory mechanism of PFKFB4 in LUAD cell proliferation, migration and invasion." (PMID 33593309, 2021). "However, the importance and exact mechanism of PFKFB4 in lung adenocarcinoma progression is lack of research." (PMID 33593309, 2021).
lung adenocarcinoma (continued). "Our results showed that knockdown of PFKFB4 suppressed lung adenocarcinoma cells proliferation, migration and invasion could be restored by SRC-2 WT overexpression but not SRC-2 S487A, indicating that PFKFB4 promoted LUAD progression dependent on SRC-2 transcriptional activity." (PMID 33593309, 2021).
small cell lung carcinoma (6 papers, 2019 to 2025). Small cell lung cancer (SCLC) is a highly aggressive malignant neoplasm, accounting for 10-15% of lung cancer cases, characterized byrapid growth, and early metastasis. "PFKFB4 seems to be positively regulated by endothelial tyrosine kinase, where depletion of either protein decreases autophagy in small cell lung cancer." (PMID 33671514, 2021). "Epithelial and endothelial tyrosine kinase (Etk) interaction with PFKFB4 modulated chemoresistance of small-cell lung cancer (SCLC) by regulating autophagy." (PMID 33593309, 2021). "Moreover, PFKFB4 can interact with endothelial tyrosine kinase to modulate chemoresistance of small-cell lung cancer by regulating autophagy." (PMID 31244553, 2019). "Moreover, PFKFB4 modulates the chemoresistance of small-cell lung cancer by regulating autophagy." (PMID 37919747, 2023).
thyroid cancer (6 papers, 2021 to 2023). "On the other hand, the knockdown of PFKFB4 inhibits invasiveness through the upregulation of histone acetyltransferase GCN5 in IHH-4 thyroid cancer cells." (PMID 37919747, 2023). "Knockdown of PFKFB4 inhibited proliferation and invasiveness in IHH-4 thyroid cancer cells, which suggests that the observed effect was mediated by upregulation of GCN5." (PMID 33671514, 2021). "Consistently, PFKFB4 is overexpressed in numerous malignancies, and its knockdown (with a molecular status comparable to haploinsufficiency) was demonstrated to inhibit proliferation and invasiveness in IHH-4 thyroid cancer cells alongside the upregulation of histone acetyltransferase GCN5." (PMID 36292148, 2022). "Moreover, a negative correlation between the expression of PFKFB4 and histone acetyltransferase GCN5 was demonstrated in thyroid cancer." (PMID 33671514, 2021).
lung carcinoma (5 papers, 2019 to 2025). "To investigate the expression of PFKFB4 in lung cancer, we analyzed data from the GEO and TCGA databases." (PMID 40213972, 2025). "PFKFB4, by interacting with Etk, promotes small lung-cancer chemoresistance through the regulation of autophagy." (PMID 34445551, 2021). "PFKFB4 expression was significantly higher in lung cancer tissues compared to normal tissues." (PMID 40213972, 2025). "Similarly, tumor tissue from lung cancer patients showed elevated protein expression of PFKFB4 compared with matched normal control tissue." (PMID 36115843, 2022).